ENG (endoglin)
Diseases named in the same sentence as ENG in open-access papers (continued):
Sharing a sentence is not in itself a finding about the gene and the disease.
preeclampsia (continued). "The placentas from patients with early-onset preeclampsia displayed increased placental endoglin expression as shown by the differential gene expression analysis, and in agreement with previous studies in women with severe preeclampsia." (PMID 34992598, 2021). "TGF-β signaling is modulated by soluble endoglin, which is also positively correlated with the soluble dermatan sulphate proteoglycan endocan in preeclampsia." (PMID 33623064, 2021). "It is known that circulating concentrations of soluble endoglin (sENG) seem to be a suitable marker to assess the severity of preeclampsia." (PMID 34671343, 2021). "The choroid is responsive to circulating angiogenic factors, such as VEGF, PlGF, and soluble endoglin, which are involved in the pathogenesis of preeclampsia." (PMID 34882742, 2021). "sFlt-1 and soluble endoglin (sEng) are antiangiogenic factors that are significantly increased in the circulation of patients with preeclampsia and are likely to play a major role in inducing endothelial dysfunction in the condition." (PMID 30659233, 2019). "Increased levels of circulating endoglin have been detected at early stages of preeclampsia in hypertensive or diabetic patients and in certain cancer patients, suggesting its role as a predictive biomarker in these pathologies." (PMID 30761306, 2019). "The authors reported significantly higher levels of sFlt-1 and endoglin and significantly lower levels of PlGF in women who developed preeclampsia but also noted that these changes are similar to those in low-risk pregnant women." (PMID 31510056, 2019). "Although previous studies have investigated the mechanism of sEng secretion and function of membrane-bound endoglin on endothelial cells and angiogenesis, there is contradictory information about the tissue origin of circulating sEng during preeclampsia." (PMID 30809262, 2019). "In vitro, MenSCs obtained from patients with a history of preeclampsia expressed less endoglin and secreted less VEGF but more IL-6 than controls did." (PMID 30809262, 2019). "Various factors including endoglin, endothelin, catechol-O-methyltransferase, or angiotensin-II are likely involved in endothelial dysfunction in pregnant or preeclampsia condition." (PMID 29311569, 2018). "Throughout pregnancy, ENG mRNA expression is elevated in the placenta and the maternal blood (cellular and cell-free components) in women who develop preeclampsia." (PMID 29580923, 2018). "A preliminary study has also demonstrated that ENG mRNA expression is significantly elevated in microvascular endothelial cells isolated from adipose tissue obtained at cesarean section in women with preeclampsia." (PMID 29580923, 2018). "Alternating O2 concentrations combined with ARNT2 or BCL6 overexpression led to the dysregulation of 11 genes (5 in the M2 and 3 in the M1 modules), including LEP, FLT1, and ENG, similar to preeclampsia." (PMID 30135684, 2018). "Although the evidence to support the alterations in ENG mRNA expression and circulating sENG protein levels is well documented across multiple studies, few studies have explored the role of ENG pathway genetic variation in preeclampsia development." (PMID 29580923, 2018). "Overall, our results provide further support for the involvement and investigation of the endoglin pathway in preeclampsia, yet additional research with larger sample sizes, including larger samples of different preeclampsia subgroups, is needed." (PMID 29580923, 2018). "Circulating levels of soluble endoglin have been shown to be higher in the serum of patients with preeclampsia, hypercholesterolemia, atherosclerosis, diabetes mellitus and hypertension, diseases which all have a significant inflammatory component." (PMID 29145462, 2017). "MMP-14 has been proposed as a potential therapeutic target to reduce circulating soluble endoglin (sEng) and mitigate clinical manifestations of preeclampsia." (PMID 28726716, 2017).
preeclampsia (continued). "Effectively soluble endoglin has been shown to be a molecule involved in the pathogenesis of preeclampsia." (PMID 29145462, 2017). "Numerous studies have shown that soluble endoglin is elevated as early as 11–13 weeks of gestation before the development of preeclampsia." (PMID 29145462, 2017). "We determined that LXRα expression positively correlated with endoglin expression in serum and placenta from patients with preeclampsia." (PMID 27736929, 2016). "Our study demonstrated dramatically higher serum endoglin levels in the preeclampsia group compared with those in the control group, and this increase was strongly positively correlated with disease severity." (PMID 27736929, 2016). "LXRα and endoglin levels in serum and placenta from patients with preeclampsia were positively correlated (serum: r = 0.486, P<0.01; placenta: r = 0.569, P<0.01)." (PMID 27736929, 2016). "LXRα and endoglin levels in serum and placenta from patients with preeclampsia were positively correlated (r = 0.486, P<0.01; r = 0.569, P<0.01)." (PMID 27736929, 2016). "Circulating levels of soluble endoglin are elevated in preeclampsia, hypercholesterolemia, diabetes, atherosclerosis, severe pulmonary arterial hypertension, acute myocardial infarction and some types of solid cancers." (PMID 26850053, 2016). "Our study determined that placental endoglin protein and mRNA levels in patients with preeclampsia were distinctly higher than those in normal controls." (PMID 27736929, 2016). "Serum and placental LXRα and endoglin levels were significantly higher in patients with preeclampsia than those in control group (P<0.05, each)." (PMID 27736929, 2016). "The objective of this study was to identify correlations between LXRα, endoglin and preeclampsia and provide new feasible methods of clinical prediction and treatment for preeclampsia." (PMID 27736929, 2016). "There were 31 cases in which endoglin levels exceeded 14.66 ng/ml in the preeclampsia group but only 3 cases in the control group." (PMID 27736929, 2016). "SolEng, proteolytically cleaved from the membrane form of endoglin, is present at high levels in a variety of pathophysiological conditions including preeclampsia." (PMID 26646071, 2016). "As expected, serum endoglin levels were also significantly higher in patients with preeclampsia than those in control group (P<0.05)." (PMID 27736929, 2016). "We confirmed several placenta proteins, such as Flt-1 and Endoglin, known to be changed in preeclampsia." (PMID 25392996, 2014). "In multiple studies, ENG gene expression (mRNA) is increased in placenta and/or cellular/non-cellular components of blood throughout pregnancy in women who develop preeclampsia." (PMID 23548068, 2013). "Additional studies are needed to validate these findings and to determine if genetic variation in ENG pathway genes impacts ENG and sENG levels in preeclampsia." (PMID 23548068, 2013). "In preeclampsia, placental concentrations of ENG mRNA are elevated throughout pregnancy and spiral artery remodeling is shallow." (PMID 23548068, 2013). "Petrozella and colleagues implicate sFlt-1 as well as soluble endoglin (sEng) proteins in human preeclampsia." (PMID 23690796, 2013). "Circulating soluble endoglin levels increased markedly beginning from 2 to 3 months before the onset of preeclampsia." (PMID 22523688, 2012). "The TGF-β1 levels are lower and the levels of soluble endoglin (sEng), a truncated form of Eng, are higher in pregnant women who subsequently develop preeclampsia than in healthy pregnant women." (PMID 22428059, 2012). "Another factor, soluble endoglin (sEng), has now been also found to be upregulated in preeclampsia in a pattern similar to sFlt1." (PMID 22685661, 2012).
preeclampsia (continued). "Moreover, endoglin activates eNOS as well as interacts and modulates Activin receptor-like kinase-1 and -5 signaling, resulting in the potentiation of Smad1 and Smad2 and inhibition of Smad3, thereby disrupting homeostasis and causing the development of preeclampsia." (PMID 22929622, 2012). "Our data strongly suggests membrane bound MMP-14 was responsible for producing soluble endoglin in preeclampsia." (PMID 22768148, 2012). "Taken together, the data suggest that endoglin plays an important role in the pathogenesis of preeclampsia." (PMID 22929622, 2012). "This study was therefore undertaken to evaluate plasma VEGFR-2 concentrations, the relative placental mRNA expression and the plasma levels after delivery in normal pregnancies and those complicated by preeclampsia in comparison to sVEGFR-1 and endoglin." (PMID 22428059, 2012). "The relative levels mRNA of VEGFR-1, sVEGFR-1 and endoglin were higher in the pregnancies complicated by preeclampsia." (PMID 22428059, 2012). "Soluble endoglin is another antiangiogenic protein, which acts to get it with sflt-1 to induce a severe preeclampsia-like syndrome in pregnant rats." (PMID 22523688, 2012). "Soluble endoglin, another anti-angiogenic protein, which acts by inhibiting TGF-β signaling, has also been shown to play a pathogenic role in preeclampsia." (PMID 22097923, 2012). "In the preeclampsia setting, low serum VEGF levels combined with elevated levels of VEGF inhibitors, such as soluble FLT-1 and soluble endoglin (sEng), cause cerebral endothelial damage and symptoms of PRES." (PMID 23243534, 2012). "Soluble endoglin (sEng) is another antiangiogenic factor isolated from the placenta and blood of women with preeclampsia." (PMID 22848831, 2012). "Soluble endoglin (sEng), a soluble receptor of transforming growth factor (TGF)-β previously associated with preeclampsia in pregnant women and with severe malaria in children, regulates the immune system and influences angiogenesis." (PMID 21966395, 2011). "In preeclampsia, the origin of Sol-endoglin seems to be the destruction of the placental vessels and/or the shedding of membrane-bound endoglin by specific membrane metalloproteases." (PMID 21171985, 2010). "A soluble form of endoglin also plays a central role in preeclampsia, a disease characterized by hypertension and severe alterations in placental circulation." (PMID 21171985, 2010). "Changes in maternal concentrations of the anti-angiogenic factors, soluble fms-like tyrosine kinase 1 (sFlt1) and soluble endoglin (sEng), and the pro-angiogenic placental growth factor (PlGF) precede the development of preeclampsia in healthy women." (PMID 20967275, 2010). "Changes in Sol-endoglin plasma levels have been reported in other pathologies different from preeclampsia, such as atherosclerosis and coronary artery disease." (PMID 21171985, 2010). "Numerous known key modulators of preeclampsia (such as Endoglin, Syncytin, human chorionic gonadotrophin -hCG-, and Glial Cell Missing Homolog -GCM1-) were modified in these transformed choriocarcinoma cells." (PMID 19079545, 2008). "Similarly, endoglin, a co-receptor of transforming growth factor-beta (TGF-β), has been implicated in endothelial dysfunction and vascular maladaptation in preeclampsia." (PMID 40218901, 2025). "For instance, soluble endoglin has been found to contribute to the pathogenesis of preeclampsia." (PMID 41039222, 2025). "Elevated CD105 (endoglin) in AF-EVs resembled augmented angiogenesis in preeclampsia." (PMID 38609955, 2024). "Furthermore, endoglin concentrations between 8 ng/mL and 10 ng/mL, depending on gestational age, have also been indicative of potential preeclampsia development." (PMID 39727876, 2024).
preeclampsia (continued). "To establish the impact of increased sEng levels in estrogen-induced cholestasis in mice treated with labetalol, we used transgenic mice overexpressing human soluble endoglin (hsEng), a recognized model of preeclampsia, and their wild-type (WT) littermates, as control." (PMID 36778021, 2023). "ENG is a trans-membrane glycoprotein and its dysregulated expression may contribute to preeclampsia." (PMID 35774506, 2022). "Additionally, preeclampsia induced up-regulation of endoglin gene expression in both tissues (1.92-fold and 2.48-fold changes in the placenta and kidney, respectively)." (PMID 36009326, 2022). "However, earlier studies have also shown that placental expression of endoglin was increased in early-onset preeclampsia versus late-onset preeclampsia, and that elevated levels of circulating endoglin were more pronounced in preterm versus term preeclampsia." (PMID 34992598, 2021). "Other increased biological markers may be regulated during first trimester environmental transition, such as soluble endoglin, which is increased in maternal sera in the case of preeclampsia." (PMID 33673360, 2021). "Therefore, endoglin seems to have a more significant role in early-onset preeclampsia than in late-onset preeclampsia." (PMID 34992598, 2021). "Soluble endoglin (sEng) is a marker of endothelial activation and is increased in preeclampsia." (PMID 33137710, 2021). "In addition to sFlt-1 and PlGF, the levels of Transforming Growth Factor 1 (TGF-β1) and its soluble receptor (soluble endoglin) are also disturbed in sera of mothers with preeclampsia." (PMID 33673360, 2021). "Therefore, sFlt-1, PlGF and endoglin are extensively assessed as potential biomarkers for the diagnosis of preeclampsia." (PMID 30090069, 2018). "We pointed out that Endoglin/CD105 is an atypical LXR target gene, which could explain how LXR could reduce the trophoblast invasion and the risk of preeclampsia." (PMID 30044452, 2018). "Moreover, soluble endoglin (sENG) protein is significantly elevated in the circulation of women with preeclampsia weeks to months before clinically overt disease." (PMID 29580923, 2018). "Furthermore, in the systemic pregnancy syndrome of preeclampsia, both, systemic inflammation and soluble endoglin, have been found elevated." (PMID 29145462, 2017). "The models of acute inflammation in the presence of circulating endoglin used in this study could allow us to approach a hypothetical onset of preeclampsia, where the presence of high levels of soluble endoglin precedes the inflammatory processes." (PMID 29145462, 2017). "In this context, the reduction of inflammation induced by circulating soluble endoglin may explain the antiangiogenic effect of soluble endoglin in the early stages of preeclampsia." (PMID 29145462, 2017). "In the future, effective suppression of placental LXRα and endoglin expression or neutralization of LXRα and endoglin activation in the circulation may provide new methods to prevent and treat preeclampsia." (PMID 27736929, 2016). "However, the relationship between LXRα and endoglin levels in serum and placenta of patients with preeclampsia remains poorly understood." (PMID 27736929, 2016). "Moreover, endoglin levels were significantly higher in patients with severe preeclampsia than those in patients with moderate preeclampsia." (PMID 27736929, 2016). "Collectively, these results indicated that serum endoglin concentration was useful for predicting preeclampsia and may be a new forecast index for clinical application." (PMID 27736929, 2016). "Additionally, endoglin levels were significantly higher in patients with early-onset preeclampsia than those in patients with late-onset preeclampsia." (PMID 27736929, 2016). "Moreover, patients with severe preeclampsia displayed significantly higher LXRα and endoglin levels than those with moderate preeclampsia (P<0.05, each)." (PMID 27736929, 2016).
preeclampsia (continued). "In conclusion, LXRα and endoglin levels may be involved in preeclampsia development and progression and may be used as biomarkers for clinical application." (PMID 27736929, 2016). "LXRα and endoglin expression in patients with preeclampsia was significantly higher than that in normal controls, and this increase was more significant in patients with severe preeclampsia." (PMID 27736929, 2016). "Complement and s-endoglin deposition in early- vs. late-onset preeclampsia (PE)." (PMID 25071773, 2014). "Complement and s-endoglin deposition in early- and late-onset preeclampsia (PE) vs. control." (PMID 25071773, 2014). "On the other hand, four proteins (Endoglin, Nox4, Flt-1 and Calretinin) were positively correlated and two proteins (AnnexinXI and PlGF) were inversely correlated with the severity of term preeclampsia (P<0.05, R value≥0.4)." (PMID 25392996, 2014). "Complement and s-endoglin deposition in preeclampsia (PE) vs. control." (PMID 25071773, 2014). "Research has identified endoglin (ENG) as a mechanism that may contribute to preeclampsia in some women." (PMID 23548068, 2013). "Endoglin has been suggested to be a major factor in the development of preeclampsia." (PMID 24391823, 2013). "Studies examining genetic regions tagged by rs10121110 and rs11792480 may provide insight into ENG’s involvement in preeclampsia." (PMID 23548068, 2013). "Our exploratory examination in black women revealed that different genes from different components of the ENG pathway (TGFβ1 and TGFβR1, but not ENG) were associated with preeclampsia compared to white women." (PMID 23548068, 2013). "It has been shown that levels of soluble fms-like tyrosine kinase (sFlt1) and soluble endoglin (sEng) are elevated while placental growth factor (PlGF) are reduced in women with diagnosis of preeclampsia and these levels correlate with disease severity and gestational age." (PMID 23110221, 2012). "Endoglin is highly increased in the maternal serum of preeclamptic women and may cooperatively act with sFlt1 to induce severe preeclampsia." (PMID 22929622, 2012). "They further suggest that, despite its well described role in the pathogenesis of preeclampsia, elevation in the baseline concentration of soluble endoglin is unlikely to underlie the increased risk of preeclampsia associated with CKD." (PMID 21886815, 2011). "Prior studies show that there is an angiogenic factor imbalance with elevated levels of antiangiogenic proteins soluble fms-like tyrosine kinase 1 (sFlt1) and soluble endoglin (sEng) and reduced levels of the proangiogenic protein, placental growth factor (PlGF) in women with preeclampsia." (PMID 22567501, 2011). "In addition to being a reliable biomarker of the disease, it has been suggested that Sol-endoglin plays a major role as an antiangiogenic factor in preeclampsia." (PMID 21171985, 2010). "A soluble form of endoglin (Sol-endoglin) has been detected in plasma, serum and urine from patients with pathologies such as preeclampsia and cancer, and its peptide sequence suggests that it is an N-terminal cleavage product of full-length, membrane-bound endoglin." (PMID 21171985, 2010). "However, accumulating evidence suggests that a broader panel of angiogenic and anti-angiogenic markers, such as PlGF, endoglin, and cystatin C, plays a crucial role in preeclampsia’s pathophysiology and may provide deeper mechanistic insights." (PMID 40218901, 2025). "However, in third-trimester placentas from severe preeclampsia, H3K27ac levels remained high over the LTR10A-ENG enhancer, suggesting that this ERV may help to maintain ENG expression unduly high in preeclampsia." (PMID 37012406, 2023). "Women with preeclampsia had 14.5% lower serum vitamin D levels than women in the control group (16.5 ng/ml vs. 19 ng/ml, p = 0.014) with 64.5% higher sFlt-1 levels (11,600 pg/ml vs. 7050 pg/ml, p < 0.001) and greater than 2 times higher endoglin levels (18.6 ng/ml vs. 8.7 ng/ml, < 0.001)." (PMID 34991614, 2022).